TPX2 (TPX2 microtubule nucleation factor)
Diseases named in the same sentence as TPX2 in open-access papers (continued):
Sharing a sentence is not in itself a finding about the gene and the disease.
cancer (continued). "Additionally, TPX2 expression was negatively related to macrophage M2 levels in 7 cancer types, but positively in GBM, MESO, and PRAD." (PMID 38315450, 2024). "PP6 depletion therefore leads to hyperactive TPX2-bound AurkA and may mimic the condition of AurkA/TPX2 complex overexpression in cancer." (PMID 39195284, 2024). "Next, using ESTIMATE, a negative association was observed between TPX2 expression and immune score and stromal score in 16 cancer types, but a positive association in KIRC and THCA." (PMID 38315450, 2024). "TPX2 expression and its prognostic value in pan-cancers were analyzed using SangerBox." (PMID 38833082, 2024). "Therefore, abnormal expression of TPX2 is of great value in predicting the development, recurrence, and metastasis of malignant tumors, including HCC." (PMID 38833082, 2024). "These previous studies have predominantly focused on TPX2 in individual cancer types." (PMID 38315450, 2024). "Further, TPX2 expression correlated with other immune cell levels in different cancer types." (PMID 38315450, 2024). "Numerous studies have reported the tumorigenic and prognostic role of TPX2 in various cancers." (PMID 38459558, 2024). "Understanding how TPX2 contributes to spindle architecture could provide useful insight into how this linchpin spindle assembly protein protects genomically unstable cancer cells." (PMID 38660563, 2024). "Additionally, TPX2 protein expression was also higher in some types of cancers including LUAD from the HPA cohort." (PMID 38315450, 2024). "Additionally, significant correlations were found between TPX2 expression and tumor microenvironment (including stromal cells and immune cells) as well as immune related genes across cancer types." (PMID 38315450, 2024). "We aim to investigate the prognostic and immunological role of TPX2 in pan-cancer." (PMID 38315450, 2024). "In certain cancers, TPX2 expression was also remarkably related to clinical stage, age, and gender." (PMID 38315450, 2024). "On these bases, the AurkA/TPX2 complex is emerging as a potential therapeutic target in cancer." (PMID 39195284, 2024). "Considering the pro‐cancer effect of TPX2, we further assessed its clinical value." (PMID 36789877, 2023). "The expression of TPX2, TOP2A and MYBL23 was significantly higher in cancer tissues than in paracancerous tissues, but SFTPB was lower in cancer tissues, and that TPX2, TOP2A and MYBL23 high expression groups had poorer OS prognosis, while SFTPB high expression group had better OS (p < 0.05)." (PMID 37407689, 2023). "TPX2 functions as a microtubule (MT)-associated protein (MAP) to modulate chromosomal instability, centrosome amplification, and the proliferation of human cancer cells." (PMID 36707511, 2023). "The elevated expression of TPX2 was also reported in multiple cancer types." (PMID 37770979, 2023). "TPX2 plays an important role in spindle orientation and is frequently upregulated in cancer." (PMID 36834736, 2023). "Additionally, TPX2 OE has been detected in several cancers, including breast cancer, liver cancer, gastric cancer, pancreatic cancer, and bladder cancer, strongly linking to a poor cancer prognosis." (PMID 36789877, 2023). "Finally, our findings suggest that TPX2 has a carcinogenic effect in many cancers and is a promising potential cancer treatment target." (PMID 36304254, 2022). "Our findings suggest that TPX2 has a carcinogenic effect on a variety of cancers and that it could be a marker of immune infiltration and poor prognosis." (PMID 36304254, 2022). "Several studies have found that a reduction in TPX2 levels is beneficial for cancer treatment." (PMID 36304254, 2022). "In this study, we performed GSEA of TPX2 and comprehensively analyzed its association with prognosis, TMB, MSI, tumor microenvironments, and immune cell infiltration in 33 cancer types through an extensive bioinformatic pan-cancer analysis." (PMID 36304254, 2022).
cancer (continued). "We next investigated the relationship between clinical data and TPX2 expression in 33 cancers." (PMID 36304254, 2022). "TPX2 has been identified as an oncogenic factor in a variety of cancers." (PMID 36225568, 2022). "While the mechanism by which TPX2 overexpression leads to cancer remains unclear, it likely involves the role of this protein in the regulation of mitotic spindle microtubules." (PMID 36304254, 2022). "We also evaluated whether TPX2 expression is related to the infiltration of immune cells in several cancers." (PMID 36304254, 2022). "Because ETS-1 is a transcription factor that functions as a primary regulator in the metastasis process by mediating the expression of MMP to degrade the ECM of cancer cells and promote the invasion or migration of cancer cells, the effect of TPX2 on the invasion of PC-3 cells was examined." (PMID 34123781, 2021). "Cancer-associated genes of the locus include ASXL1, DNMT3B, BCL2L1, TPX2, KIF3B and POFUT1." (PMID 34577783, 2021). "Moreover, combination of suppressing the TPX2 activity and interrupting its expression would further arrest the proliferation of cancer cells, which offers new therapy strategies." (PMID 32723329, 2020). "TPX2 is tyrosine phosphorylated in malignant transformed 16HBE-C, and this phosphorylation may be involved in the malignant proliferation of cancer cells." (PMID 32626756, 2020). "Then pathway enrichment results suggested that TPX2 may facilitate tumorigenesis by participating in several cancer-related signaling pathways in LUAD, especially in Notch signal pathway." (PMID 33029085, 2020). "TPX2 had been proved to be overexpressed in many malignant tumors and promoted tumor deterioration." (PMID 32766313, 2020). "All these results suggested that TPX2 may facilitate tumorigenesis by taking part in several cancer-related signaling pathways in LUAD." (PMID 33029085, 2020). "The uncontrolled expression of TPX2 may eventually become the driving force of cancer development by inducing aneuploidy." (PMID 32626756, 2020). "Using bioinformatic analysis, we revealed that TOP2A could be adopted as a prognostic indicator of NSCLC and it potentially regulate cancer development through co-work with TPX2." (PMID 31528121, 2019). "All the bioinformatic analysis and qRT-PCR experimental results support the hypothesis that TOP2A potentially regulate NSCLC cancer development through co-work with TPX2." (PMID 31528121, 2019). "Since TPX2 depletion preferentially affects cell survival in BRCA2-depleted cancer cells and because TPX2 functions in mitotic spindle assembly, we examined whether progression through mitosis is aberrant in BRCA2-deficient cells." (PMID 30177840, 2019). "Moreover, recent works on TPX2 in DNA damage response opened an extended therapeutic window for TPX2-targeted therapies in cancer." (PMID 31119182, 2019). "Since Aurora kinase A, which is associated with TPX2, is currently tested as a therapeutic target in cancer treatment, we investigated whether BRCA2-mutant cancer cells were more sensitive to chemical inhibition of Aurora-A." (PMID 30177840, 2019). "Moreover, TPX2 silence resulted in G2-M arrest, apoptosis and the suppression of cell migration and invasion of cancers." (PMID 31417870, 2019). "The result revealed that both TOP2A and TPX2 expressed much higher in cancers (both LUAD and LUSC) comparing to normal lung tissues, and Pearson correlation analysis results showed that TOP2A expression was highly similar to TPX2, R = 0.59, 0.79 in LUAD and LUSC respectively." (PMID 31528121, 2019). "Specifically, AURKA and TPX2 together with MYC appear to act as driver genes in MYC-driven cancers." (PMID 30177840, 2019). "In several types of cancers, the overexpression of TPX2 has been reported." (PMID 30305064, 2018). "Previous studies have revealed that TPX2-siRNA could decrease the viability and proliferation capacity of cancer cell lines." (PMID 30305064, 2018).
cancer (continued). "Moreover, TPX2 inactivation experiments indicated anti-proliferative effects in cancer cells, suggesting the potential value of TPX2 as an anti-cancer target." (PMID 30100882, 2018). "TPX2 plays an important role in the mechanism of paclitaxel’s activity against cancers." (PMID 28069036, 2017). "TPX2 has been shown to bind to Aurora A through its N-terminal segment with 2.3 nM affinity and inhibitors of the TPX2/Aurora A interaction have been suggested to serve as potential therapeutic agents for cancer treatments." (PMID 28444399, 2017). "Moreover, both genes are part of the chromosomal instability signature that was found to predict clinical outcome for different cancers with TPX2 having the highest CIN score." (PMID 27148480, 2016). "TPX2 knockdown reduced prostate-specific antigen (PSA) expression in PCa cell lines, indicating that TPX2 regulates AR signaling in PCa, and induced cell cycle arrest, apoptosis, and the inhibition of cell proliferation and invasion in multiple other cancers." (PMID 27626693, 2016). "TPX2 was initially identified as a proliferation marker with a potential role in human cancer." (PMID 27148480, 2016). "Increasing evidences indicate that the aberrant expression of TPX2 may play an important role in the invasion and progression of human cancers." (PMID 25302620, 2014). "The role of TPX2 in cancer progression has been well characterized." (PMID 24625450, 2014). "Moreover, RanGAP1-specific siRNAs also inhibited the expression of Aurora kinases and TPX2, the key regulators of mitotic cell division, and clinical indicators of aggressive cancers." (PMID 24223200, 2013). "In addition to playing a critical role in cancer cell proliferation and tumorigenesis, TPX2 appears to be involved in metastasis, as it is tightly cell-cycle regulated." (PMID 24341487, 2013). "Interestingly, TPX2 is known to be highly expressed in various cancer tissues, and it has been suggested as a biomarker for poor prognosis." (PMID 22761906, 2012). "When stratified by resection margin status (positive vs. negative), both DPEP1 and TPX2 were associated with cancer-specific mortality in resection margin positive patients (P<0.01, Kaplan Meier log rank)." (PMID 22363658, 2012). "Integration of the recurrent regions identified by WACE and the gene regulatory network analysis uncovered not only many well-known oncogenes like BIRC5and E2F1, but also a number of novel cancer susceptibility genes such as ECT2, TPX2 and TACC3, which are involved in cell cycle and ECM regulation." (PMID 21806811, 2011). "However, the regulation of TPX2 activity and its subsequent effects on mitosis and cancer progression remain unclear." (PMID 40107714, 2025). "However, to our knowledge, many studies on TPX2 mainly focused on a specific cancer type." (PMID 38315450, 2024). "Then, we aimed to investigate whether the alteration TPX2 affects prognosis in different cancers." (PMID 38315450, 2024). "Up-regulated TPX2 could predict worse outcomes in the majority of cancers." (PMID 38315450, 2024). "Together, these results indicate an important function of TPX2 in regulation of AurkA interphase localization and suggest that it may play a role, independent of its activating function, in nuclear enrichment of the kinase in cancer." (PMID 36797043, 2023). "Likewise, TPX2 has been studied as a factor critical for mitosis and spindle assembly and as a marker for diagnosis and prognosis when overexpressed in cancer; GTSE1 can also act as an oncogene and a high expression was positively correlated with histological grade and poor survival." (PMID 35954157, 2022). "Therefore, cancer cell lines may already display deregulated levels of mitotic factors and the actual effect of increased TPX2 levels on an unperturbed mitosis would be more precisely addressed using non-cancer cells." (PMID 32041138, 2020). "Moreover, TPX2 is also a marker of poor tumor prognosis in several cancers." (PMID 32285914, 2020).
cancer (continued). "Meanwhile, numerous studies suggest that TPX2 may be a target for cancer treatment." (PMID 31272499, 2019). "Finally, TPX2 is frequently co-overexpressed with Aurora-A in cancer, suggesting that the complex may constitute a novel therapeutic target." (PMID 28389630, 2017). "Moreover, TPX2 expression is a marker of worse tumor prognosis in several cancers." (PMID 28069036, 2017). "The identified protein-protein interaction inhibitors of the Aurora-A/TPX2 complex might represent lead compounds for further development towards pioneering anti-cancer drugs and provide the proof-of-concept for a new exploitable strategy to target mitotic kinases." (PMID 28389630, 2017). "Many studies suggest that decreasing TPX2 levels may be a beneficial approach for cancer treatment." (PMID 28069036, 2017). "Targeting specifically the TPX2-activated Aurora A may open new strategies in cancer therapy." (PMID 27148480, 2016). "However, the precise role of TPX2 in cancer progression is still not fully understood." (PMID 25914189, 2015). "Two genes, IQGAP3 and TPX2, were upregulated at the mRNA level but showed protein-level downregulation (IQGAP3 in all cancers; TPX2 in BRCA and COAD, up in LUAD), indicating post-transcriptional repression." (PMID 41439026, 2025). "The results showed that TPX2 and BIRC5 were upregulated, while AGER, TEK, CLIC5, MAMDC2, EMCN, and SEMA3G were mostly downregulated in multiple cancer types." (PMID 40535574, 2025). "By employing ComBat to correct for batch effects in our study and focusing on the top DEGs, we highlighted genes such as TPX2, MKI67, EXO1, and CTHRC 1, which exhibited progressive upregulation from infection to cancer." (PMID 40445003, 2025). "Genes such as TPX2, MKI67, EXO1, and CTHRC1 exhibited progressive upregulation from infection to cancer, highlighting involvement in cell cycle regulation, DNA repair, and extracellular matrix remodeling." (PMID 40445003, 2025). "The focused heatmap of the top 10 DEGs highlighted genes such as TPX2, MKI67, EXO1, and CTHRC1, which showed progressive upregulation from infection to cancer." (PMID 40445003, 2025). "Identifying hub genes such as TPX2, MKI67, and EXO1, which are involved in cell cycle regulation and DNA repair, further supports the cancer-specific relevance of our biomarkers." (PMID 40445003, 2025). "Among them, TPX2 depletion is a well-known biomarker in ESCA cells, leading to reduced cancer cell growth and invasion ability." (PMID 38769480, 2024). "We found that in the case of the ALT high TEL high phenotype, genes TRIP13, TPX2, and MCM7 were upregulated in eight cancer types and ADAMTS8 in seven cancer types was downregulated." (PMID 38763334, 2024). "Among the upregulated genes, we observed strong overexpression of TPX2 and MCM2, which regulate cell proliferation during cancer development." (PMID 38584841, 2024). "Proliferative cancer cells highly expressed proliferation-related genes (MKI67, TOP2A, and TPX2); they also had the highest CytoTRACE score, reflecting strong proliferative potential and higher stemness characteristics." (PMID 37853464, 2023). "Since TPX2 is upregulated in HCC tissues, we then screened the expression levels in TCGA pan-cancer RNA sequencing data." (PMID 36204642, 2022). "Withanone is reported to bind to the TPX2/AURKA complex which results in the dissociation of TPX2 from AURKA and disruption of mitotic spindle apparatus in cancer cells." (PMID 33451333, 2021). "A panel of eight cancer driver genes (CCNE1, TPX2, ELF3, FANCL, JAK2, GSK3B, CEP76, and SYK) were differentially expressed in recurrent TNBCs, and were also overexpressed in TCGA and METABRIC." (PMID 30665374, 2019). "Besides the cell division-associated genes like CCNB2 and BUB1B, we also found genes such as TPX2, BIRC5, TOP2A, SPAG5 and HMGB1, were among the top 10 highly expressed genes in the cell subset, which were reported to be directly or indirectly associated with cancer invasion." (PMID 31888172, 2019).
cancer (continued). "Most of the interacting genes, including FAM83D, TPX2, and AURKA, are all located on 20q, which is frequently amplified across many cancer types." (PMID 29088801, 2017). "Collectively, these observations raise a strong possibility that FAM83D coordinates cell cycle progression in human cancer cells by binding with HMMR, TPX2, and AURKA." (PMID 29088801, 2017). "Fourteen genes that are essential to prevent EDR in cancer cells also are essential to prevent aneuploidy in mice [AURKA, BUB1B, BUB3, KIF11, MAD2L1, TPX2, TTK, SGOL1." (PMID 27144335, 2016). "All cancer samples expressed AIM1 mRNA at higher levels than any of the non-malignant samples; while ERGIC1 was over-expressed in 94% (n = 31), and TPX2 in 64% (n = 23) of the cancer samples." (PMID 22761906, 2012). "TPX2 is an activator of AURKA (aurora kinase A), which is overexpressed in cancer and regarded as a key regulator of mitosis." (PMID 23029477, 2012). "Pan-cancer analysis showed widespread dysregulation of TTC26 and TPX2." (PMID 40599775, 2025). "Moreover, based on the blue module genes screened by WGCNA and existing researches, AURKA, TPX2, CHEK1, and PLK1 were found to be highly related to NCAPH and were involved in the regulation of PI3K/AKT pathway in cancer." (PMID 38587786, 2025). "More importantly, the inhibition of lactate production via an LDHA inhibitor or TPX2 lactylation significantly suppressed in vivo HCC tumour growth, suggesting that TPX2 lactylation may serve as potential targets for new cancer interventions." (PMID 40107714, 2025). "TPX2 and TTC26 are mainly significantly upregulated in a variety of malignant tumors." (PMID 40599775, 2025). "Based on Gene Set Cancer Analysis (GSCA), we found that TPX2 copy number variation (CNV) was positively related to its mRNA expression in different cancers, suggesting that CNV could be a factor in the modification of TPX2." (PMID 38315450, 2024). "Patients with TPX2 elevated expression were likely to be sensitive to many anticancer drugs based on the Cancer Therapeutics Response Portal (CTRP) and Genomics of Drug Sensitivity in Cancer (GDSC) database." (PMID 38315450, 2024). "The first described PPI inhibitor was Withanone, a natural compound that blocks intermolecular hydrophobic interactions between TPX2 and AurkA involved in the formation of the complex, hindering its functionality and impairing mitotic spindle organisation in MCF7 cancer cells." (PMID 39195284, 2024). "Negative correlations between TPX2 methylation and TPX2 expression were observed across multiple human cancers." (PMID 38315450, 2024). "TPX2 had a positive correlation with TMB in 20 cancer types, while negative correlations were observed in COAD and THYM." (PMID 38315450, 2024). "Gedevo alignments are also related to multiple cell cycle functions, and some of them show evidence of dysregulation in cancer (ASPM, CENPF, TOP2A, and TPX2) and the acquisition of two hallmarks of cancer: sustaining proliferative signaling and evading apoptosis." (PMID 36661515, 2023). "Among the 33 cancer types, UCS had the highest TPX2 expression, whereas KICH had the lowest." (PMID 36304254, 2022). "Whereas TPX2 overexpression has been observed in a variety of cancers, no thorough pan-cancer investigation of TPX2 has previously been performed." (PMID 36304254, 2022). "Notably, overexpression of TPX2 led to increased PARP1 activity and thus to increased PARP trapping potential, providing an explanation for why high TPX2 mRNA levels in cancer cells correlate with increased sensitivity to PARP trapping inhibitors." (PMID 36350633, 2022). "High levels of TPX2 are reported in tumours and the effects of its overexpression have been investigated in cancer cell lines, while little is known in non-transformed cells." (PMID 32041138, 2020). "In this work, we investigated the effects of increased levels of the MT-binding protein TPX2, frequently overexpressed in cancer, in non-transformed human cells." (PMID 32041138, 2020).